ITGB4 (integrin subunit beta 4)
Diseases named in the same sentence as ITGB4 in open-access papers (continued):
Sharing a sentence is not in itself a finding about the gene and the disease.
cancer (continued). "Increased expression of ITGB4 and ITGA5 are associated with poor cancer prognosis with increased cancer migration and invasion." (PMID 38339062, 2024). "The ITGB4/FAK signaling pathway is critical in regulating a diverse array of downstream molecules and signaling cascades associated with cancer cell metastasis." (PMID 39169946, 2024). "We observed a significant downregulation of ITGB4 in dormant as compared to the proliferating cancer cells in vivo, and in 2-DG-treated as compared to vehicle-treated cancer cells in vitro, while the expression of ITGB1 was unaltered." (PMID 37456245, 2023). "We also identified MRP1 (ABCC1), a protein responsible for chemoresistance and typically upregulated in cancer cells, and ITGB4, which has a key role in tumorigenesis." (PMID 37295717, 2023). "Among the downstream genes, FN1, cadherin 2 (CDH2), EGFR, integrin subunit alpha 6 (ITGA6), and integrin subunit beta 4 (ITGB4), which are widely studied and are associated with cancer metastasis, were selected for further investigation." (PMID 37096833, 2023). "Altogether, our results suggest that KCNF1 increases ITGB4 expression and signaling that disrupt cell adhesion and basement membrane integrity, thereby promoting cancer progression and metastasis." (PMID 36385523, 2023). "NETs‐DNA enhanced endogenous binding of ITGB4 to integrin‐linked kinase (ILK), a putative mediator of NETs‐driven cancer metastasis, leading to recruitment of β‐parvin, but not α‐parvin or PINCH, to mobilize the small GTPases RAC1 and CDC42." (PMID 37828611, 2023). "Recent studies have demonstrated that ITGB4 is involved in tumorigenesis and metastasis during the development of cancer." (PMID 37371594, 2023). "Although the array of published studies has revealed the potential diagnostic and prognostic value of ITGB4 in large varieties of cancer, accurate expression patterns and prognoses of ITGB4 in OSCC are still incompletely understood." (PMID 37371594, 2023). "It seems that the proportion and cell numbers of double-positive ITGB4 and PD-L1 cancer cells (ITGB4+PD-L1+) was high in the OSCC specimen, and the statistical result approached a significant difference (positivity p = 0.07, positive number p = 0.06)." (PMID 37371594, 2023). "Prior to conducting our work, evidence had begun to accumulate evidence that indicated that ITGB4 exhibits an aberrant expression and frequently correlates with malignant progression in a board range of carcinomas." (PMID 37371594, 2023). "Meanwhile, we observed a significant elevation of ITGB4 expression with the increase of cancer stage of ccRCC." (PMID 35305660, 2022). "HNSCC cancer stem cell (CSC) marker CD44, integrin beta 4 (ITGB4), and small GTPase Rac2 were linked to the terms “Cell leading edge”, “Cell-substrate junction”, and “Focal adhesion”, while further genes showed linkages to one or two GO-terms." (PMID 36076232, 2022). "Although its functional significance in CCM disease remains to be elucidated, it is noteworthy that ITGB4 expression is increased on various cancer cells and is thought to be involved in the regulation of cancer stem cells." (PMID 35661927, 2022). "Cancer entities with highest ITGB4 expression in single malignant cells were compared (log(TPM/10 + 1) > 0.5)." (PMID 36076232, 2022). "Our recent study identified differential effects of ITGB4 splice variants on the migration of esophageal squamous cells and found ITGB4E is uniquely associated with decreased cancer cell migration." (PMID 35250607, 2022). "ITGB4 is one of the integrin (ITG) molecules that is associated with cell migration, proliferation, and cancer development." (PMID 34361106, 2021). "The implications of ITGB4’s oncogenic potential and contribution to CSCs make this integrin subclass an appealing immunological target for cancer treatment." (PMID 34504657, 2021). "Kajiji et al38 and Desgrosellier et al10 demonstrated that ITGB4 expression levels were significantly increased in a variety of malignancies." (PMID 34414684, 2021).
cancer (continued). "ITGB4 was reported to be involved in cell death, autophagy, angiogenesis, senescence, and differentiation and to regulate the development of different cancers and diseases of the nervous system." (PMID 31242404, 2020). "BNIP3L-dependent mitophagy and reverse Warburg effect was induced in CAFs through the uptake of cancer cell-derived exosomal ITGB4." (PMID 32957712, 2020). "Further studies have reported that high expression levels of ITGB4 were found in several types of cancer—including breast, bladder, colon, ovarian, pancreatic, prostate, and thyroid—and were linked to poor prognosis." (PMID 30658712, 2019). "In vitro and in vivo experiments indicate that ITGB4 promotes tumorigenesis and metastasis in different types of cancers." (PMID 30361615, 2019). "Our previous investigation found that MARVELD1 regulated the expression of ITGB1 and ITGB4 in cancer cells." (PMID 30250269, 2018). "Previous studies showed that MARVELD1 expression is lower in tumour cells, and MARVELD1 regulates the balance of ITGB1 and ITGB4 expression in cancer cells." (PMID 30250269, 2018). "As a receptor for the laminins, ITGB4 is essential for the organization and maintenance of epithelial structure and plays a pivotal role in the metastasis of various cancer cells." (PMID 28864908, 2018). "Integrin β4 (ITGB4) is a transmembrane receptor involved in tumorigenesis and the invasiveness of many cancers." (PMID 28084395, 2017). "Inspired by the previous studies and given that ITGB4 is highly expressed in cancer cells, in the current study we focused on the roles of ITGB4 nuclear translocation in controlling cancer cell apoptosis." (PMID 26918348, 2016). "Here, for the first time, we report that a chiral small molecule, SEC, selectively promotes apoptosis in cancer cells expressing a high level of ITGB4 by inducing ITGB4 nuclear translocation." (PMID 26918348, 2016). "The identification of compounds that are highly selective for ITGB4 high-expressing cancer cells has been advancing but challenging." (PMID 26918348, 2016). "This study provides a powerful proof of concept for using the nuclear translocation of ITGB4 as a therapeutic strategy to combat various ITGB4-related cancers." (PMID 26918348, 2016). "Future studies will involve experimental as well as spontaneous metastasis assays to determine the contribution of FAK activation to ITGB4-dependent carcinoma progression." (PMID 24533083, 2014). "It is conceivable that Zeb1 during gastrulation also regulates other targets controlling cell behavior, as shown for specific laminin (LAMC2) and integrin (ITGB4) genes in cancer cells." (PMID 23667256, 2013). "Moreover, a meta-analysis of ccRCC identified ITGB4 as a target gene regulated by microRNA-204 (miR-204), further emphasizing the importance of ITGB4 in the context of cancer progression." (PMID 39169946, 2024). "ITGB4 emerges as a key player with diverse regulatory mechanisms across different cancers." (PMID 39169946, 2024). "Studies on triple-negative breast cancer (TNBC) found that cancer cell-derived exosomal ITGB4 could be delivered to CAFs to induce BNIP3L-dependent mitophagy and lactate production in CAFs." (PMID 36899389, 2023). "ITGB4 is highly expressed in various cancers and contributes to tumor progression." (PMID 36899389, 2023). "Combined blockade of ITGB1 and ITGB4 may be a promising approach to inhibit intrahepatic colonization of DCCs, thereby preventing cancer metastasis and recurrence." (PMID 37828611, 2023). "Furthermore, considering the positive prognostic role of activated T cells in cancers, we explored a subgroup of patients with a high co-expression of ITGB4, PD-L1, CD8 and PD-1." (PMID 37371594, 2023).
cancer (continued). "Accumulating evidence has owed ITGB4’s abnormal expression in cancers to different regulations." (PMID 35305660, 2022). "However, a large and growing body of literature has characterized the complex role of ITGB4 in cancer biology." (PMID 35250607, 2022). "Therefore, ITGB4 has been attracting world wild interest in disclosing its roles in human diseases, especially cancers." (PMID 35305660, 2022). "Moreover, many recent studies suggest that overexpression of ITGB4 accelerates metastasis of different cancer cells via regulating the process of epithelial-mesenchymal transition (EMT)." (PMID 35305660, 2022). "ITGB4, also known as integrin β4, could regulate apoptosis, migration, invasion, and signal transduction of cancer cells through forming α6β4 with Integrin α6." (PMID 33748101, 2021). "The expression of ITGB4 was increased only in cancer tissues." (PMID 34414684, 2021). "Altered expression of ITGB4 has been observed in various cancers including lung and breast." (PMID 34624066, 2021). "Further investigation into the synergistic relationship between IFN-γ and IL-6 may provide insight into how these ITGB4-targeted immunotherapies function in vivo, and potentially provide additional effort to improve cancer therapeutic efficacy." (PMID 34504657, 2021). "Surprisingly, it seems like that the more obvious the silencing of ITGB4 is, the less the migration and motility of cancer cells will be impaired, and the more obvious the silencing of ITGB7 is, the stronger the migration and movement ability of cancer cells is." (PMID 32127932, 2020). "ITGB4 overexpression was related to the aggressiveness and poor prognosis of many malignant tumors." (PMID 33335550, 2020). "Together, these data implied that ITGB4 is necessary for promoting cancer stem-like properties." (PMID 30658712, 2019). "Integrin β4 (ITGB4) has been reported to be involved in carcinomas." (PMID 31602273, 2019). "ITGB4 promotes invasion and migration in various cancer cells." (PMID 28864908, 2018). "In this study, we identified a new chiral small molecule, SEC, that could promote cancer cell apoptosis by inducing ITGB4 nuclear translocation." (PMID 26918348, 2016). "Thus, the Pareto marker approach is consistent with the outstanding role of ITGB4 in predicting dasatinib response in cancer cells." (PMID 26083411, 2015). "Furthermore, ITGB4 appears to influence FAK phosphorylation in various cancers." (PMID 39169946, 2024). "Similarly, LE-LE cancer cells could signal through adhesive ligand-receptor pairs LAMB3-ITGA6_ITGB4 and LAMB3-ITGA6_ITGB1, and inflammatory ligand-receptor pairs MIF-CD74_CD44." (PMID 37596273, 2023). "ITGB4 expression patterns display a strong heterogeneity and may vary between different carcinomas." (PMID 37371594, 2023). "This study suggests that ITGB4-induced mitophagy could be a novel target for cancer therapy." (PMID 33511121, 2020). "Thus, the heterogeneity of cancer might explain the apparent different role for ITGB4 and LCN2 in PCa." (PMID 30931931, 2019). "At the individual gene level, ITGA8 and ITGA9 were down-regulated in 11 out of the 15 cancers, whereas ITGAX, ITGB4, and ITGA6 were more frequently up-regulated in tumors relative to adjacent normal tissues (right)." (PMID 39436262, 2024). "As a transmembrane receptor, ITGB4 mainly binds to laminin in the ECM and regulates tumorigenesis and invasiveness of many cancers." (PMID 39456433, 2024). "This study revealed that YKL40, of which the secretion was enhanced through the interaction between cancer cells and macrophages, is involved in EOC progression by promoting the proliferation, migration, and invasion of cancer cells via ITGB4." (PMID 39408927, 2024). "Considering the fact that ITGB4, ITGA2, and ITGA6 were frequently up-regulated in cancer vs. normal tissues, our results suggest potential protumorigenic roles for them." (PMID 39436262, 2024).
cancer (continued). "This pancancer gene set includes key integrins (e.g. ITGA6, ITGB1, ITGB4) and their interconnectors (e.g. SPP1, TGFBI), affirming their critical role in the cancer adhesion resistome." (PMID 37206618, 2023). "Since ITGB4-positive cancer stem cell (CSC)-enriched mesenchymal cells were found to reside in an intermediate epithelial/mesenchymal phenotypic state, ITGB4 can be used to enable stratification of mesenchymal-like TNBC cells." (PMID 37787041, 2023). "During the early phases of the metastatic process, carcinoma cells often undergo EMT, where adherence junctions (ECAD), apical tight junctions (ZO‐1), and basolateral hemidesmosomes (ITGB4) are disassembled." (PMID 34890102, 2022). "And the results showed a higher expression of JUP and ITGB4 in cells expressing CD44 or CD24, which were cell markers of cancer stem cells." (PMID 34402716, 2021). "In the CCLE database, expression of JUP, ITGB4, ST8SIA5, ST8SIA1, ST3GAL2, ST3GAL5 and B4GALNT1 in pan-cancer were explored." (PMID 34402716, 2021). "Numerous studies have suggested that ITGA11, ITGB4 and ITGB8 are involved in migration, epithelial-mesenchymal transition, invasion, and metastasis in different cancers." (PMID 31875161, 2019). "To further investigate the role of ITGB4 in GSCs, we enriched cancer stem cells from LN229 and U251 cells by mammosphere formation assay and then knocked down ITGB4 expression in these cells using siRNA." (PMID 30658712, 2019). "Previous studies showed that MARVELD1 mediated the balance between ITGB1 and ITGB4 in cancer cells through down-regulating the expression of ITGB1 in mRNA processing and up-regulating ITGB4 by binding its promoter." (PMID 30250269, 2018). "Laminin-332 can interact with two types of integrins, ITGA6/ITGB4 (α6β4) and ITGA3/ITGB1 (α3β1), and activation of laminin-332-mediated integrin signalling enhances cancer cell development and metastasis." (PMID 29423074, 2018). "The expression of many genes that induce adhesion, such as CXCR4 and DCN, and cellular movement in cancer, such as DKK1 and ITGB4, evidently increased when FLRT2 was downregulated, and decreased when FLRT2 was upregulated." (PMID 28325946, 2017). "We identified a small molecule, SEC, with selective pro-apoptosis effects on cancer cells with high expression of ITGB4, both in vitro and in vivo, by triggering the binding of ITGB4 and ANXA7, ITGB4 nuclear trafficking, and pro-apoptosis gene expression." (PMID 26918348, 2016). "CD104 [integrin beta 4 (ITGB4)] mediates cell-matrix or cell-cell adhesion, enhances cell growth and signaling, and thus plays a pivotal role in cancer invasion." (PMID 27655682, 2016). "Consistent with previous reports that FAK is activated by ITGB4 and mediates ITGB4-dependent cell motility, our data also suggest that ITGB4 is an essential mediator of FAK activation and cancer cell motility." (PMID 24533083, 2014). "Using gene network analysis we selected 3 significantly upregulated cell movement and cancer related genes for further analysis: EPCAM (epithelial cell adhesion molecule), ITGB4 (integrin β4) and PLAU (urokinase-type plasminogen activator (uPA))." (PMID 24885350, 2014). "The study further revealed that ITGB4+PD-L1+ cancer cells, but not ITGB4+ALDH1+ cancer cells, were significantly associated with the infiltration of CD8+ T cells (positivity p = 0.005, positive number p = 0.03)." (PMID 37371594, 2023). "However, despite a previously published article predicting that ITGB4 may be overexpressed at mRNA level in ccRCC, studies so far have neither validated its expression condition nor demonstrated any of its biological functions and molecular mechanisms in this cancer." (PMID 35305660, 2022). "Involvement of ITGB4 in migration/invasion, stemness, and EMT is documented for several carcinomas." (PMID 36076232, 2022).
cancer (continued). "Furthermore, we found that some ITGs such as ITGA3, ITGA6 ITGA11, ITGB4, ITGB6, etc. were frequently upregulated in human cancers, whereas ITGs including ITGA1, ITGA7, ITGA8, ITGA9 and ITGB3, etc. were usually downregulated." (PMID 34222028, 2021). "So, we hypothesized that cancer stem cells maybe essential in the regulatory mechanism of JUP and ITGB4." (PMID 34402716, 2021). "Targeting integrin β4 (ITGB4) combined with ILK could increase the latent tumorigenic potential and decrease the invasive potential in cancer." (PMID 34966737, 2021). "ITGB4, which forms a dimer with integrin α6 (ITGA6), has been widely studied in carcinomas." (PMID 34414684, 2021). "Additionally, deletion of TMEM268 facilitates the disintegration of ITGB4 and Plectin, impairs FLNA stability and the F-actin network, which eventually leads to cytoskeletal remolding in cancer cells." (PMID 30361615, 2019). "The aberrant expression of ITGA11, ITGB4, and ITGB8 have been reported in many cancers." (PMID 31875161, 2019). "Furthermore, the secretion of YKL40 induced by the interaction between EOC cells and macrophages was shown to enhance the phosphorylation of Erk via ITGB4, thereby promoting the migration and invasion of EOC cells, suggesting its significant role in cancer progression." (PMID 39408927, 2024). "In contrast, ITGB4+ALDH1+ cancer cells were not correlated with CD8." (PMID 37371594, 2023). "Notably, none of these pairs have been directly associated with TGFβ signaling or EMT, although many of the identified ligands (e.g., LAMC2) or receptors (e.g., CD151, COL17A1, ITGA2, ITGA3, ITGA6, ITGB1, and ITGB4) occur frequently in the context of EMT and/or cancer." (PMID 36755019, 2023). "However, selective therapeutic strategies against cancer cells expressing a high level of ITGB4 have not been reported." (PMID 26918348, 2016). "However, the growth-inhibitory effect of ITGB4 in carcinoma cells is not clear." (PMID 26918348, 2016).
infection (7 papers, 2015 to 2025). The state of being infected such as from the introduction of a foreign agent such as serum, vaccine, antigenic substance or organism. "In addition, the infection caused by A. hydrophila resulted in significant changes in the transcription of epithelial proliferation and migration-related genes, including tp63, fat2, and Itgb4, when compared to control fish." (PMID 37908355, 2023). "ITGB4 directly interacts with the E glycoprotein of Zika virus, mediating its attachment, entry, and infection of host cells." (PMID 41440381, 2025). "RSV infection (MOI=5) significantly down-regulated ITGB4 expression at 6 hpi (hours post infection) and 12 hpi." (PMID 35958591, 2022). "Correlation analysis showed that the duration of decreased ITGB4 expression was inversely proportional to infection virulence." (PMID 35958591, 2022). "On day 4 and day 6 post infection, goblet cells in the bronchial lumen of ITGB4-/- mice were significantly proliferated and mucus secretion was greatly increased, whereas ITGB4+/+ mice showed no obvious goblet cell proliferation and mucus secretion." (PMID 34975337, 2022). "A hard-thresholded, mostly relaxed, LASSO-constrained logistic regression model was used to select a parsimonious gene set (ITGB4, ITGA7, IFI27, FAM20A) highly capable of discriminating any bacterial from nonbacterial infection (cross validated AUC = 0.90)." (PMID 40060038, 2025).
bacterial infection (2 papers, 2020 to 2025). "Density plots for the selected genes displayed separate, but overlapping expression patterns with ITGA7, ITGB4 and FAM20A exhibiting higher expression in subjects with bacterial infection and the interferon-related gene IFI27 exhibiting higher expression in subjects lacking a bacterial infection." (PMID 40060038, 2025).
gastrointestinal disorders (1 paper, 2019). "Three other SNPs (rs313279811, rs316340790 and rs732847450) were annotated in the ITGB4 gene, positional candidate for GIZZP, and these genetic variants can result in epidermal and gastrointestinal disorders." (PMID 31438838, 2019). "In humans, several studies reported both lethal and nonlethal variants in ITGB4 gene responsible for epidermal and gastrointestinal disorders." (PMID 31438838, 2019).